INS (insulin)
Diseases named in the same sentence as INS in open-access papers (continued):
Sharing a sentence is not in itself a finding about the gene and the disease.
diabetes (continued). "The use of SC insulin injections for diabetes care is negatively impacted by the need to educate patients and train them on injection techniques and the requirement for refrigeration or cooling below room temperature during transportation and storage." (PMID 38641565, 2024). "The two datasets share seven common features: age, eGFR, HbA1c, insulin intake, sex, body-mass index, and of course diabetes past duration." (PMID 38435625, 2024). "If the degree of insulin is under scrutiny, social variables have a negligible impact on these complications of diabetes." (PMID 38357071, 2024). "Diabetes mellitus is a metabolic disorder characterized by the body's inability to produce or respond to insulin properly, so it cannot regulate blood sugar levels at normal levels." (PMID 38827017, 2024). "Relevant articles published up to July 28, 2022, were extracted from PubMed and Embase using the MeSH (Medical Subject Headings) terms of the defined keywords [(short-chain fatty acids) AND (obesity OR diabetes OR insulin sensitivity)] and their synonyms." (PMID 37290429, 2024). "Several peptides, such as insulin and incretin mimetics, have been used as therapeutic options for diabetes mellitus." (PMID 39337311, 2024). "Continuous subcutaneous insulin infusion for the treatment of diabetes mellitus Technology appraisal guidance [TA151]; 2008." (PMID 38504346, 2024). "Diabetes is a metabolic disorder in which carbohydrate metabolism is disrupted due to either insufficient production of insulin or impaired sensitivity of cells toward insulin." (PMID 38370077, 2024). "In other clinical settings, diabetes self-management using insulin pumps, for example, during short surgeries, is commonplace." (PMID 38163872, 2024). "We thus investigated lung samples from INSC94Y transgenic pigs, a tailored large animal model for mutant INS gene-induced diabetes of youth (MIDY), characterized by impaired insulin secretion, β-cell loss, and chronic hyperglycaemia." (PMID 38900131, 2024). "Icodec insulin is one of two ultra-slow, weekly-acting analogues currently being studied to treat diabetes." (PMID 38672255, 2024). "It is known that insulin concentration varies with age even in cognitively healthy individuals with diabetes." (PMID 38586183, 2024). "All these changes, including malfunction of beta pancreatic cells accompanied by cellular apoptosis, lead to a reduction in the number of pancreatic β cells, ultimately resulting in decreased insulin production and hyperglycemia, leading to diabetes." (PMID 39064493, 2024). "He developed post-transplant diabetes mellitus in the immediate post-transplant period and started insulin therapy by multiple daily injection scheme." (PMID 38779453, 2024). "Increased oxidative stress and inflammation in the mother during pregnancy can increase insulin secretion function, triggering alterations in sugar metabolism; approximately one-sixth of pregnant females develop diabetes." (PMID 39502878, 2024). "In 2014–2017, 83% of participants with diabetes who were on treatment were taking oral antidiabetic medications only, 8% were taking insulin only, and 9% were taking a combination." (PMID 38232087, 2024). "Methodology A retrospective chart review was conducted of adult insulin-treated patients at the Chertow Diabetes Center, Huntington, WV, who were started on GLP-1 RAs for 24 months." (PMID 38854306, 2024). "She worked with two other nurses in the Unitarch consortium to determine the net influence of the regimented diabetes insulin administration on the long-term control of blood sugar among elderly patients (attributes–professional skills)." (PMID 39767451, 2024). "In other words, muscle strengthening enhances insulin activity, glucose consumption, and muscle glycogen storage, thereby decreasing the incidence of diabetes." (PMID 38276133, 2024).
diabetes (continued). "The choice of including only diabetologists in the panel relays to the fact that in Italy patients on insulin therapy are largely in charge of specialistic diabetes centers." (PMID 38767675, 2024). "Overall, the ability of seaweed polysaccharides to modulate glycemic response and improve insulin sensitivity makes them promising candidates for the development of new treatments for diabetes." (PMID 38667785, 2024). "The landmark Diabetes Control and Complications (DCCT) trial found that the use of intensive insulin therapy in T1D reduced the risk of long-term microvascular complications, but that intensive therapy also increased the risk of hypoglycaemia." (PMID 38875308, 2024). "Glycaemia, diabetes distress and patient and provider satisfaction were assessed during the first 3 months after initiating basal insulin titration using the mobile app." (PMID 38812671, 2024). "Diabetes mellitus is a chronic metabolic disorder characterized by a high blood glucose level, either because of impaired insulin secretion or insulin resistance by the cells." (PMID 38496195, 2024). "Both aerobic (endurance) and resistance exercise contribute to improved glycemic control and insulin sensitivity in individuals with diabetes." (PMID 39795939, 2024). "Type II diabetes (T2DM) is the most common form of diabetes, characterized by the body’s inability to synthesize and secrete insulin, which prevents the intake of glucose and leads to the subsequent rise of blood glucose levels." (PMID 38523640, 2024). "Other researchers tried to classify ICI-DM based on the presence of diabetes-specific autoantibodies and the level of endogenous insulin production." (PMID 39518461, 2024). "Type 2 diabetes mellitus (T2DM) is a chronic and progressive condition defined by hyperglycemia caused by abnormalities in insulin production, insulin receptor sensitivity, or both." (PMID 38232103, 2024). "One of these diseases is Diabetes mellitus (DM), characterized by alterations in insulin secretion, action, or both." (PMID 39273161, 2024). "Cognitive dysfunction makes it difficult for older patients with diabetes to perform complex self‐management tasks, such as monitoring blood glucose and adjusting insulin dosage, and they also affect patients' eating times and meal rationalization." (PMID 38571669, 2024). "After a diagnosis of LAD at any age, patients require regular follow-up with glucose, glycated hemoglobin, and C-peptide measurements to assess the need for insulin therapy to prevent diabetic ketoacidosis and long-term diabetes complications." (PMID 39329041, 2024). "Diabetes is a disease characterized by high blood glucose that occurs when the pancreas is unable to produce enough insulin or when the body is unable to use insulin effectively." (PMID 39287315, 2024). "Before the breakthrough discovery of insulin, historical understandings and treatments of diabetes laid essential groundwork, albeit limited by the knowledge of the time." (PMID 39691108, 2024). "Metformin is a commonly used drug for treating diabetes mellitus (DM), which reduces glucose levels and improves insulin sensitivity." (PMID 39768389, 2024). "While insulin therapy is essential for controlling blood glucose levels in diabetes, it can lead to episodes of hypoglycemia, especially if the dosage is not carefully monitored or the patients are not well instructed." (PMID 39728296, 2024). "Diabetes is a group of carbohydrate metabolism disorders characterized by chronic hyperglycemia, resulting from insufficient insulin secretion, defective action, or both." (PMID 39713052, 2024). "Diabetes is characterized by chronic hyperglycemia resulting from defects in insulin secretion, insulin action, or both." (PMID 38686257, 2024). "Insulin replacement therapy is the cornerstone for the maintenance of optimal glucose levels and circumventing long-term complications in people with type 1 diabetes mellitus (T1DM)." (PMID 36896906, 2024).
diabetes (continued). "Diabetes mellitus is characterized as a metabolic disorder resulting from compromised carbohydrate, lipid, and protein metabolism stemming from inadequate insulin function." (PMID 39403720, 2024). "Phosphorylation of IRS-2 at Ser731 has been shown to be significantly increased in nervous tissue in diabetes, contributing to the development of resistance to insulin." (PMID 39057034, 2024). "Diabetes mellitus (DM) is a chronic metabolic disease characterized by high blood sugar resulting from impaired insulin secretion, defective insulin action, or a combination of the two." (PMID 38955832, 2024). "The interruption of previously established antidiabetic medication, especially insulin, is one of the most important factors leading to the deterioration of diabetes." (PMID 39063405, 2024). "The risk prediction model included eight predictors as follows: duration of diabetes, urinary microalbumin, oral hypoglycemic agents, mild cognitive impairment, insulin usage, hypertension, blood glucose monitoring, and abdominal circumference." (PMID 39610841, 2024). "Diosgenin lowers the damage of diabetes by altering cellular pathways for pancreatic β cell renewal for improved secretion of insulin and modifying ER-α-mediated PI3K/Akt pathways." (PMID 38371502, 2024). "Insulin resistance, defined as diminished sensitivity and reactivity to insulin, was a key indicator of type 2 diabetes mellitus." (PMID 39055055, 2024). "Less stringent targets are advisable only in particular situations associated with patient-centered therapy, such as limited access to insulin analogs and diabetes technology and psychological burden." (PMID 39201842, 2024). "Its expression is decreased in the pancreatic beta cells of diabetes, with experimental depletion resulting in blunting of glucose-induced insulin response and promoting beta cell de-differentiation." (PMID 39561140, 2024). "Forth, a substantial portion of data regarding oral medications or insulin usage before cardiac arrest was unavailable for patients diagnosed with diabetes, leading to an inadequate basis for analysis." (PMID 38330019, 2024). "The pathophysiology of diabetes mellitus is driven by two mechanisms: the reduced insulin secretion by the β-cells of the pancreas and the insulin resistance by the insulin-sensitive tissues in the body, such as the muscles, liver, and adipose cells." (PMID 39165448, 2024). "All participants stated that parents play a pivotal role in self-management because they constantly encourage, remind, and assist their children with diabetes-related tasks like food preparation and buying and keeping insulin supplies." (PMID 39315319, 2024). "Diabetes mellitus (DM) is a chronic disease resulting from an inherited and acquired deficiency in the production of insulin by the pancreas (type 1 DM) or from the ineffectiveness of the insulin produced (type 2 DM)." (PMID 39715819, 2024). "Impaired transmission between any of the components of the insulin cascade leads to reduced insulin sensitivity and diabetes." (PMID 39478961, 2024). "The features in this dataset are the number of times pregnant, Glucose, Blood Pressure, Skin Thickness, Insulin, BMI, Diabetes pedigree function, and age in years format." (PMID 38718024, 2024). "For people living with diabetes, access to affordable treatment, including insulin, is critical to their survival." (PMID 39120188, 2024). "ML highlighted age, use of insulin, diabetes duration, and tyrosine as the most influential factors in DKD and DR." (PMID 38546730, 2024). "High insulin and blood glucose levels, the hallmarks of patients with Diabetes, serve as growth factors for cancer development." (PMID 38831236, 2024). "Conversely, this correlation appeared similar across different genders, ages, races, BMI categories, hypertension statuses, and insulin usage among people with diabetes (all p for interaction >0.05)." (PMID 39850479, 2024).
diabetes (continued). "If immunotherapy-associated DKA is diagnosed in hospital, patients require admission for multidisciplinary medical care and stabilization, transition to an outpatient insulin regimen, and diabetes education." (PMID 39726058, 2024). "More recently, islets derived from neonatal GalTKO.hCD55.hCD59 source pigs demonstrated cure of diabetes with >1 year of insulin independence in the stringent pig-to-baboon model." (PMID 38476227, 2024). "We show that, over time, mortality trends in our population with diabetes improved and that individuals managed with insulin had significantly higher mortality over all time periods." (PMID 39358593, 2024). "The search strategy employed typical keywords, including “irisin” “irisin and exercise”, “irisin and disease”, “irisin and aging”, “irisin and insulin and diabetes”, and “irisin and brain”." (PMID 39769243, 2024). "Diabetes is characterized by hyperglycaemia, target-tissue resistance to insulin, and insufficient insulin secretion." (PMID 39062940, 2024). "Long-term insulin treatment would still be needed for a few days to weeks in cases achieving remission, and client education regarding diabetes management and glycemic home monitoring is mandatory." (PMID 38539988, 2024). "The liver mainly controls the circulating level of sFNDC4, and the reduction of liver factor FNDC4 leads to pre-diabetes in mice, that’s because sFNDC4 promoted insulin signal transduction and insulin mediated glucose uptake in white adipocytes." (PMID 39325938, 2024). "Effective implementation of the insulin PDA through the strategies identified can facilitate doctors in discussing diabetes management with patients thereby improving patient-doctor communication." (PMID 39546450, 2024). "GLP-1 has demonstrated its efficacy in treating diabetes and obesity by utilizing multiple mechanisms, including stimulating insulin secretion, inhibiting glucagon secretion, protecting β cells and decreasing food intake." (PMID 38440398, 2024). "We report the case of a patient who had been following up in the endocrinology clinic for a primary diagnosis of type 1 diabetes mellitus with occasional findings of bruises at insulin injection sites." (PMID 39479124, 2024). "Our study provides a better understanding of the role of KCNQ1 in regulating insulin secretion and β-cell survival in hereditary diabetes pathology." (PMID 39055936, 2024). "Silibinin targets various pathophysiological mechanisms of diabetes by increasing insulin levels, reducing insulin resistance, and lowering hyperglycemia." (PMID 38726421, 2024). "During the course, the parents emphasized that they have primary responsibility for diabetes care, including estimations of insulin doses and carbohydrate estimations." (PMID 38892551, 2024). "Diabetes self-management requires lifelong commitment to numerous highly complex tasks including glucose monitoring, insulin dose adjustments and administration, hypoglycaemia management, self-coordination and planning." (PMID 39138689, 2024). "The VIVID study compared MDI versus CSII administered U500 insulin and noted a significantly greater Treatment Related Impact Measure for Diabetes score in the CSII group compared with the MDI group." (PMID 39215657, 2024). "In the early treatment groups, insulin (3 U/day, subcutaneously) and WJMSCs-CM (10 mg/week, intraperitoneally) were administered immediately after diabetes induction; in the late treatment groups, these interventions began 30 days postinduction." (PMID 39391856, 2024). "Significant effects of increasing age, duration of diabetes, HbA1c, sexual maturation stage, and insulin administration schedule (insulin/kg) were observed on the increase in TG values." (PMID 38534969, 2024). "Mitochondria-targeted antioxidants, regulators of energy homeostasis, and the MPT pore formation demonstrated beneficial effects on mitochondrial capacity and function, insulin sensitivity, and diabetes-related cell damage." (PMID 39334925, 2024).
diabetes (continued). "Suppression of USP1 has been demonstrated to improve diabetes outcomes by the inhibition of DNA damage, preventing pancreatic β cell apoptosis, preserving insulin secretion, and enhancing β-cell maturation in human islets." (PMID 38322269, 2024). "Discovering how secretory factors from other organs can influence insulin-producing cells to maintain glycemic control continues to be valuable in understanding the pathophysiology and management of diabetes." (PMID 38782979, 2024). "Despite presenting with DKA, up to half of the children with obesity who presented with DKA at initial diagnosis of diabetes successfully discontinued insulin therapy within a median period of 1.25 months." (PMID 38765897, 2024). "Diabetes mellitus, characterized by high blood glucose due to inadequate insulin action, comprises two main types: type 1, an autoimmune disease, and type 2, marked by insulin resistance." (PMID 39840001, 2024). "This program covers fundamental aspects like diabetes pathogenesis, insulin types, and dosing, as well as managing ketosis and hypoglycemia." (PMID 38590482, 2024). "The high molecular weight and diverse structural forms of D‐Glcp within CSPsN‐1 can reduce glucose production and absorption while enhancing insulin sensitivity, making it beneficial for diabetes therapy." (PMID 39479660, 2024). "Type 2 diabetes mellitus (T2DM) is a chronic metabolic disorder characterized by hyperglycemia as a result of the reduced sensitivity of tissues to insulin and beta-cell dysfunction, eventually leading to insulin secretion deficit." (PMID 39167349, 2024). "The next target of our research is to use the possible active compounds for in vivo experiments to find out the effective antihyperglycemic compounds for the treatment of diabetes that work the insulin-independent pathway." (PMID 39885962, 2024). "The primary treatment for autoimmune Diabetes Mellitus (Type 1 Diabetes Mellitus-T1DM) is insulin therapy." (PMID 38396657, 2024). "It downregulates ten-eleven-translocation protein 3 (TET3) and impairs the DNA demethylation at the paternal alleles of several insulin secretion genes such as glucokinase (GCK), thus making the offspring susceptible to impaired glucose tolerance and diabetes." (PMID 39353925, 2024). "In patients with diabetes, insulin-stimulated uptake and utilization of glucose are impaired and energy metabolism in cardiomyocytes is altered due to the defects in insulin-mediated actions or insulin resistance." (PMID 38628588, 2024). "After adjusting for confounding factors like age, diabetes duration, and insulin use, the odds of advanced CKD were approximately 4.6 times higher in non-proliferative DR (NPDR) and 11.8 times higher in PDR compared to those without DR." (PMID 39872596, 2024). "Diabetes mellitus (DM) is a chronic metabolic and endocrine disorder arising from inadequate insulin secretion or resistance, presenting a substantial global public health challenge." (PMID 39323632, 2024). "For the treatment of diabetes, insulin has been delivered transdermally through microdevices, mostly through microneedle array-based, minimally invasive injections." (PMID 38509342, 2024). "Diabetes mellitus, characterized by chronic hyperglycemia due to insulin secretion defects, poses significant health and economic burdens." (PMID 38831300, 2024). "Often, patients perceive the initiation of insulin therapy as a failure in effectively managing their diabetes." (PMID 38559691, 2024). "Synthetic oral anti-hyperglycemic drugs such as insulin, sulfonylureas, thiazolidinediones and biguanides were successfully developed for diabetes treatment." (PMID 38673748, 2024). "Insulin therapy and oral drugs such sulfonylureas, biguanides, -glucosidase inhibitors, and glinides are often used to manage diabetes." (PMID 39003280, 2024). "GDM is different from type 1 diabetes mellitus where the level of insulin is low due to malfunctioning pancreatic gland." (PMID 39035597, 2024).